MTOR (mechanistic target of rapamycin kinase)
Diseases named in the same sentence as MTOR in open-access papers (continued):
Sharing a sentence is not in itself a finding about the gene and the disease.
endometrioid carcinomas of ovary (2 papers, 2023 to 2024). "However, the PI3K/AKT/MTOR pathway is also complex, and currently PI3K and AKT inhibition may be most promising in clear cell and endometrioid carcinomas of ovary." (PMID 39104720, 2024).
endometritis (2 papers, 2022 to 2024). An acute or chronic, usually bacterial infectious process affecting the endometrium. "Moreover, studies on endometritis show that derangement of mTOR signaling is linked to the establishment of endometrial dysfunction caused by chronic inflammation." (PMID 35408777, 2022). "In conclusion, CA inhibits inflammation and ferroptosis by regulating AMPKα/mTOR/HIF‐1α signalling pathway to alleviate S. aureus‐induced endometritis in mice." (PMID 39462269, 2024).
energy metabolism disorder (2 papers, 2023 to 2025). "Therefore, our findings also suggested that energy metabolism disorder mediated autophagy via AMPK/mTOR axis in the context of 4-OP poisoning in common carp hearts, which requires further investigation." (PMID 40559415, 2025). "In this study, LFT alleviated AKT/mTOR expression and AKT phosphorylation inhibited by LF, suggesting that LFT could alleviate apoptosis and energy metabolism disorder caused by LF." (PMID 37891958, 2023).
enteritis (2 papers, 2021 to 2025). Inflammation of the small intestine. "Importantly, we found that mTOR inhibitor not only reduces enteritis but also synergistically improved the anti-tumor immune response by triggering the immunogenic cell death (ICD) of tumor cells." (PMID 34987517, 2021).
Erythema (2 papers, 2024). Redness of the skin, caused by hyperemia of the capillaries in the lower layers of the skin. "Over the course of 24 weeks, a reduction in the size and erythema of the patient’s FAs was observed, alongside improvements in social engagement, suggesting potential added benefits of systemic mTOR inhibition beyond tumor control." (PMID 39727664, 2024). "By six months into the treatment regimen, both the size and erythema of the facial angiofibromas had visibly diminished, indicating a noteworthy and somewhat unexpected therapeutic response of these lesions to systemic mTOR inhibition with everolimus." (PMID 39727664, 2024).
esophagitis (2 papers, 2015 to 2016). An acute or chronic inflammatory disease affecting the esophageal wall. "The phospho-mTOR was considered ‘negative’ i.e., cytoplasmic membranous staining was undetected, or merely observed in a few cells; The latter was found in 10 cases of pill-induced esophagitis, 9 cases of reflux esophagitis and 5 cases of the control group, respectively." (PMID 26047496, 2015).
gingival cancer (2 papers, 2020 to 2024). A primary or metastatic malignant neoplasm that affects the gums. "Chlorpromazine increases autophagy-related proteins and inhibits mTOR, PI3K, Akt, and p70S6K, inducing autophagy and apoptosis in gingival cancer cells." (PMID 39840028, 2024). "Potential antitumor drugs like chlorpromazine have also been found to induce autophagy in gingival cancer cells by upregulating autophagy-related proteins (Atg5, Atg7, Atg12, Beclin-1, and LC3A/B-II) while downregulating negative regulators (mTOR, PI3K, Akt, and p70S6K)." (PMID 39840028, 2024). "In the present study, our results demonstrated that mTOR is not involved the cytotoxicity of ZnO-NPs in gingival cancer cells." (PMID 32111101, 2020). "Interestingly, ZnO-NPs suppressed the phosphorylation of p70S6K, but had no obvious inhibition on the phosphorylated level of mTOR, which therefore excluded the role of mTOR in ZnO-NP-induced apoptosis on gingival cancer cells." (PMID 32111101, 2020).
glycogenosis (2 papers, 2017 to 2025). "By inhibiting glycogenosis, glucuronic acid creates a cellular energy deficit that inactivates the nutrient-sensitive mTOR pathway." (PMID 40427416, 2025).
GM2 gangliosidosis (2 papers, 2021 to 2023). A group of recessively inherited diseases characterized by the intralysosomal accumulation of G(M2) GANGLIOSIDE in the neuronal cells. "Our work thoroughly and systematically shows that autophagy/lysosome/mTOR-associated molecules might be useful markers for monitoring the effects of potential therapeutic approaches beyond GM2 gangliosidosis." (PMID 34831346, 2021). "We contend that the pathological mTOR signalling and consequential mitochondrial and lysosomal dysfunction that we report in GM2 gangliosidosis immediately suggest avenues for therapeutic exploration." (PMID 34831346, 2021). "However, modulation of mTOR with a physiological compound, L-arginine, if effective offers a largely non-invasive option for opportune exploration in GM2 gangliosidosis." (PMID 34831346, 2021).
hairy cell leukaemia (2 papers, 2016 to 2023). "The potential role of AKT/mTOR signalling proteins and its association with the Raf-MEK-ERK pathway was investigated in hairy cell leukaemia (HCL)." (PMID 26893254, 2016).
Hansen disease (2 papers, 2019 to 2025). "DEGs related to neurological and immunological terms identified IDO-1, mTOR signalling, TLR, T-cell, MAPK and Notch Pathways as important players in leprosy progression in susceptible hosts." (PMID 40788929, 2025). "Rapamycin, a well-known mTOR inhibitor 41, is the most common drug used to treat patients with Hansen disease." (PMID 31660081, 2019).
Hashimoto’s disease (2 papers, 2025). "The FAO level in EAT mice significantly increased, indicating that changes in FAO are not only related to the mTOR signaling pathway but also associated with the unique metabolic pattern of Hashimoto’s thyroiditis itself." (PMID 39641893, 2025). "In Hashimoto’s disease, the expression level of mTOR protein in thyroid tissue is higher than in normal thyroid tissue, and therefore less autophagy occurs in thyroid tissue." (PMID 40956676, 2025). "Considering this study on the treatment of MTC, it is thought that studies evaluating new treatments targeting the SESN/AMPK/mTOR pathway in Hashimoto’s disease are needed." (PMID 40956676, 2025). "It has been shown that autophagy regulated by the mTOR signaling pathway is effective in Hashimoto’s disease." (PMID 40956676, 2025). "Expression of mammalian target of rapamycin (mTOR), which plays a key role in coordinating the balance between cell growth and autophagy, is elevated in thyroid tissues of patients with Hashimoto’s disease." (PMID 40956676, 2025). "When we interpret this finding in conjunction with previous studies in the literature, we suggest that the decrease in SESN2 levels in Hashimoto’s disease may lead to increased mTOR expression, ultimately resulting in suppressed autophagy." (PMID 40956676, 2025). "The known relationship between SESN2 and mTOR suggests that the high mTOR levels observed in Hashimoto’s disease may be due to low SESN2 levels in patients, as in PTC." (PMID 40956676, 2025). "The mTOR/ACC1/CPT1A fatty acid oxidation pathway of CD4+T cells in Hashimoto’s thyroiditis was increased, and treatment with Etomoxir could inhibit the activation of this pathway, and reverse the reprogramming of abnormal metabolism in CD4+T cells, thereby reducing Hashimoto’s thyroiditis." (PMID 39641893, 2025).
hematoma (2 papers, 2014 to 2022). A hematoma is a collection of blood from a vascular structure into an extravascular space. "Increased p-mTOR, which mean that mTOR signaling was activated, was predominantly located around the hematoma." (PMID 24602288, 2014). "The increased p-mTOR was predominantly located around the hematoma." (PMID 24602288, 2014). "Our study provides the first evidence that the mTOR signaling pathway is abnormally activated in brain after ICH, especially around the hematoma." (PMID 24602288, 2014).
histiocytic sarcoma (2 papers, 2014 to 2024). An aggressive malignant neoplasm with a poor response to therapy, usually presenting as stage III/IV disease. "Note, a previous report showed that animals with increased mTOR signaling as a result of a Pten mutation in HSCs using Mx1Cre mice also developed histiocytic sarcomas." (PMID 25201874, 2014).
Hyperammonemia (2 papers, 2017 to 2019). An increased concentration of ammonia in the blood. "Although hyperammonemia was reported to upregulate MSTN and inhibit downstream mTOR pathway, no changes have been found in the mRNA expression level of MSTN and protein expression level of mTOR signal pathway after ammonia exposure." (PMID 31861338, 2019).
idiopathic multicentric Castleman disease (2 papers, 2020 to 2024). "Recently, IL-6 stimulation augmented mTOR activation in idiopathic multicentric Castleman disease (iMCD) patients was reported, furthermore, the degree of mTOR activation in iMCD was comparable to ALPS." (PMID 33489922, 2020). "Recent advancements in the treatment of idiopathic multicentric Castleman disease (iMCD) have pointed to the efficacy of sirolimus, an mTOR inhibitor, particularly in cases that have not responded to traditional IL-6 inhibitors." (PMID 38927348, 2024).
ileitis (2 papers, 2025). "The mTOR inhibitor rapamycin significantly alleviated NE-induced ileitis, showing a villus arrangement, long villi, and short crypts with attenuated histopathological scores of 2.4 vs. 7.6 for the NE birds." (PMID 40284599, 2025). "Together, these results suggest that mTOR signaling mediates C. perfringens-induced ileitis, and combining mTOR inhibition and DCA improves the intervention efficacy against NE ileitis and BWG loss." (PMID 40284599, 2025).
Incisional hernia (2 papers, 2021). An abdominal hernia that occurs at a site of weakness in the abdominal wall resulting from an incompletely-healed surgical wound. "Immunosuppression, in particular, mTOR (a mammalian target of rapamycin) inhibitors, has been correlated with incisional hernia, HAT, rejections, and risk of cancer development." (PMID 34355016, 2021). "A recent meta-analysis demonstrated a higher rate of incisional hernia (3.7 to 18.1% (p < 0.001)) and wound complications in patients treated with mammalian target of rapamycin (mTOR) inhibitors (e.g. Sirolimus) compared to mycophenolate mofetil." (PMID 34112231, 2021).
insomnia (2 papers, 2022 to 2025). A sleep disorder characterized by difficulty in falling asleep and/or remaining asleep. "Additionally, resveratrol's treatment of insomnia is closely linked to the SIRT1, AMPK, NF-κB, mTOR, PI3K/Akt, and MAPK pathways." (PMID 40144750, 2025). "In tumor-induced insomnia and sleep-wakefulness cycle disorder, orexin of the central nervous system may inhibit the autophagy of tumor cells through mTOR-dependent PI3K/Akt tumor signal pathways." (PMID 35794987, 2022).
intestinal tumors (2 papers, 2013 to 2025). "S. flexneri C.11 and its metabolites enhanced the binding of ERBB3 to Nrg1, activating the PI3K-AKT and mTOR pathways, which subsequently promoted the malignant transformation of normal intestinal epithelial cells and progression of intestinal tumors in mice." (PMID 40911847, 2025).
iron overload (2 papers, 2021). "In another study, deletion of mTOR from cardiomyocytes in an iron-overload mouse model showed mTOR was protective against iron toxicity and apoptosis of the cardiac cells." (PMID 35058797, 2021).
ischemia reperfusion injury (2 papers, 2021 to 2025). Adverse functional, metabolic, or structural changes in ischemic tissues resulting from the restoration of blood flow to the tissue (reperfusion), including swelling; hemorrhage; necrosis; and damage from free radicals. "Leucine accumulation, resulting from impaired BCAA metabolism, triggers both mTOR-mediated cell death and PPARα-enhanced FA oxidation, leading to increased cardiac lipid toxicity and vulnerability to ischemia-reperfusion injury." (PMID 40182633, 2025).
juvenile polyposis syndrome (2 papers, 2018 to 2020). Juvenile gastrointestinal polyposis (JIP) is a rare condition characterized by the presence of juvenile hamartomatous polyps in the gastrointestinal (GI) tract. "Diseases associated with the protein coding gene BMPR1A include juvenile polyposis syndrome and polyposis syndrome, and this gene has been shown to be related to the mammalian target of rapamycin (mTOR) and PI3K/AKT signaling pathways." (PMID 31998776, 2020).
kidney stone (2 papers, 2021 to 2025). "The previous study has proposed that the deregulated MTOR signaling and the impairment in autophagy represent promising targets for suppressing kidney stone development." (PMID 34489936, 2021). "Due to their involvement in the control of the adipocytokine signaling route, PPAR signaling pathway, mTOR signaling pathway, and fatty acid production, DE-FRGs may contribute to the etiology of kidney stones." (PMID 40171220, 2025). "These marker genes may be involved in the control of the PPAR signaling pathway, mTOR signaling system, and fatty acid production of kidney stones, according to the functional enrichment analysis that followed." (PMID 40171220, 2025). "Genes in this crosstalk include those previously reported to be of functional relevance to nephrolithiasis, such as protein kinase C (PRKCA, PRKCB, and PRKCZ), markers (CD40 and TLR3), and autophagy (MTOR and SQSTM1), thus validating our genetic prioritization at the gene and pathway level." (PMID 34489936, 2021).
leukocytosis (2 papers, 2022 to 2025). "Moreover, when we treated the injured WT and NSE-BMP4 mice with the mTOR inhibitor rapamycin for 2 weeks, the rapamycin-treated NSE-BMP4 mice still had high ActA levels, even though these animals exhibited the same blockade in HO and attenuated leukocytosis that we observed earlier." (PMID 36289197, 2022).
Lewis lung carcinoma (2 papers, 2021). "For instance, cardamomin inhibited the invasion and metastasis of Lewis lung carcinoma cells through inhibiting mTOR activity." (PMID 34812264, 2021).
Li-Fraumeni syndrome (2 papers, 2022 to 2025). "GBOs have also been used to study response to chimeric antigen T (CAR-T) cell immunotherapy in the setting of the EGFRvIII variant, mTOR inhibitors in PTEN loss, and STAT inhibitors in Li-Fraumeni syndrome." (PMID 35978801, 2022).
liver failure (2 papers, 2024 to 2025). A liver disease characterized by the liver losing or has lost all of its function. "IL-10 secreted by transplanted MSCs activated the mammalian target of rapamycin (mTOR) pathway and thereby enhanced mitochondrial function as well as correct abnormal lipid metabolism in treating post-hepatectomy liver failure." (PMID 39497124, 2024).
lymphangioleiomyomas (2 papers, 2018 to 2025). "Another mTOR inhibitor, everolimus, has recently been used for treatment of LAM in open-label studies; this agent could also stabilise lung function and reduce AML and lymphangioleiomyomas with tolerable safety when administered in low doses." (PMID 30428897, 2018).
malignant meningioma (2 papers, 2021). "Chrysophanol may be useful as a treatment against malignant meningioma by inhibiting OGN/mTOR signaling and activating NF2 signaling." (PMID 33622177, 2021).
mastocytosis (2 papers, 2024). A clonal myeloproliferative neoplasm characterized by the proliferation and accumulation of neoplastic mast cells in one or multiple organs or organ systems. "We also found TCP1 to be predicted in mastocytosis and B-cell precursor-ALL, whose high expression has been associated with AML drug resistance and poor survival through the activation of AKT/mTOR signaling." (PMID 38769532, 2024). "Abnormal activation of the mammalian target of rapamycin (mTOR) complexes may play a role in mastocytosis." (PMID 38275618, 2024).
measles (2 papers, 2020 to 2022). A highly contagious viral infection caused by the measles virus.
MELAS (2 papers, 2022 to 2025). "Indeed, in a small clinical study, the mitochondrial disease phenotypes of four kidney transplant patients with mitochondrial disease (MELAS) improved after the immunosuppressant was replaced with rapamycin to achieve mTOR inhibition." (PMID 35872650, 2022).
meningitis (2 papers, 2020 to 2022). A disorder characterized by acute inflammation of the meninges of the brain and/or spinal cord. "We began our investigation of the drivers of autophagy-related PI3K/Akt/mTOR signaling pathway in E. coli K1–infected HBMEC by hypothesizing that the NT playing a detrimental role in HBMECs' defense against E. coli meningitis may act as an infection-associated regulator of autophagy." (PMID 33042863, 2020). "In another 2 cases (#6 and #7), after therapy with sirolimus was initiated, mTOR inhibition resulted in complete resolution of chronic infections (Streptococcus pneumoniae—meningitis and Campylobacter—pericarditis)." (PMID 35676905, 2022).
mental retardation syndrome X-linked (2 papers, 2020 to 2024). "For sporadically occurring PNETs, MEN1, DAXX (death domain associated protein), ATRX (α-thalassemia/mental retardation syndrome X-linked), and genes related to the mammalian target of rapamycin (mTOR) pathway harbor commonly identified somatic alterations." (PMID 38279330, 2024). "For example, common somatic mutations in PanNET include MEN1 (multiple endocrine neoplasia type 1), DAXX (death-domain-associated protein)/ATRX (alpha alassemia/mental retardation syndrome X-linked), and mTOR (mammalian target of rapamycin) pathway genes." (PMID 33101770, 2020).
Miscarriage (2 papers, 2020 to 2024). A pregnancy that ends at a stage in which the fetus is incapable of surviving on its own, defined as the spontaneous loss of a fetus before the 22th week of pregnancy. "Mammalian target of rapamycin (mTOR) signaling is important for the growth of fetal organs and its dysregulation is associated with miscarriage." (PMID 33371356, 2020). "Therefore, mTOR signaling is important for the growth of fetal organs, and its dysregulation may lead to miscarriage or recurrent miscarriage." (PMID 33371356, 2020). "These were stated to correlate with miscarriage rate in previous studies.RPS6, is a substrate for inducible phosphorylation, downstream effector of mTOR pathway." (PMID 38777848, 2024).